AXL (AXL receptor tyrosine kinase)
Diseases named in the same sentence as AXL in open-access papers (continued):
Sharing a sentence is not in itself a finding about the gene and the disease.
breast carcinoma (continued). "Similar to AXL inhibition, it has shown that Elmo knockdown suppressed the proliferation and invasion of breast cancer cells." (PMID 27829217, 2016). "Inhibition of AXL decreased migration and invasion in breast cancer cells and reduced cancer cell proliferation, survival, and tumor growth." (PMID 27590506, 2016). "We demonstrated that AXL expression was higher in all triple-negative mesenchymal-like breast cancer cell lines, compared with luminal/epithelial cells." (PMID 28721387, 2016). "Selective AXL inhibition impaired the activity of M2-like macrophages, reducing cancer cell invasiveness, and restoring the sensitivity of breast cancer cells to chemotherapeutic drugs." (PMID 28721387, 2016). "Another study found overexpression of AXL in breast cancer stem cells; inhibition of AXL decreased NF-κB activity, expression of EMT-associated genes, invasion, and tumor formation." (PMID 27058560, 2016). "In primary breast cancers, AXL expression independently predicts poor overall patient survival, and AXL expression is enhanced in the metastatic lesions of matched patients." (PMID 27829217, 2016). "Here, we found that AXL expression was positively correlated with poor progression in breast cancer patients." (PMID 27590506, 2016). "Previous investigators proposed that vimentin, an intermediate filament protein, functionally contributes to EMT activation and is required for AXL upregulation, which contributes to the lung extravasation of breast cancer cells in mice." (PMID 27829217, 2016). "The Oncomine database also showed that AXL expression was positively correlated with advanced tumor stages and lymph node status of breast cancer patients, suggesting that AXL is crucial for tumor progression and survival outcomes in breast cancer patients." (PMID 27590506, 2016). "In this study, we found that inhibition of AXL (E1A gene therapy or R428) increases the sensitization of breast cancer cells to EGFR-TKI." (PMID 27590506, 2016). "Recent findings have demonstrated that AXL potently promotes invasion and metastasis in experimental models, and AXL expression correlates with poor outcomes with breast cancer patients." (PMID 27829217, 2016). "Recent studies have also reported that activation of AXL is involved in the development of EGFR inhibitor resistance in breast cancer cells." (PMID 26356563, 2015). "Breast cancer with epithelial-to-mesenchymal transition (EMT) phenotype predicts inferior outcome, and AXL has been shown to be an essential regulator of EMT in breast cancer." (PMID 26356563, 2015). "In certain cancers including breast cancer, AXL mRNA and protein levels were found to be higher in tumor metastases compared to primary tumors." (PMID 26356563, 2015). "AXL, a member of the TAM receptor tyrosine kinase subfamily, has been previously implicated in the pathophysiology of multiple cancers, including breast cancer." (PMID 26356563, 2015). "To further evaluate AXL protein expression in TNBCs, we performed immunohistochemical (IHC) staining of AXL using a set of breast cancer tissue microarrays containing 57 TNBC tumor cores with patient survival data." (PMID 26356563, 2015). "AXL has been identified as a predictor of poor prognosis for several types of malignancies, including breast cancer, pancreatic cancer, lung adenocarcinoma, osteosarcoma, oral squamous cell carcinoma, and acute myeloid leukemia." (PMID 26573603, 2015). "It has also been demonstrated that AXL expression correlates with motility and invasiveness in breast cancer cells." (PMID 25337673, 2014). "AXL is overexpressed in highly invasive breast cancer cell lines (such as Hs578T, BT549, MDA-MB-435s, MDA-MB-157, MDA-MB-436, and MDA-MB-231); in contrast, weakly invasive breast cancer cell lines do not or only weakly express AXL." (PMID 25337673, 2014). "Another previously reported interacting partner of ACK1, AXL has been shown to regulate cell migration and invasion in breast cancer." (PMID 24461128, 2014).
breast carcinoma (continued). "For example, vimentin expression was shown to be required for the induction of AXL expression and such regulation functionally contributed to the EMT phenotype in breast cancer cells and accordingly silencing of vimentin decreased AXL levels significantly." (PMID 25337673, 2014). "AXL is another receptor tyrosine kinase known to be involved in ovarian cancers; AXL promoted proliferation in glioma cells and breast cancer cells, and AXL upregulation and activation was detected in ovarian cancers over normal ovaries." (PMID 21962244, 2011). "Next, we assessed AXL mRNA and protein expression levels in a set of breast cancer cell lines." (PMID 41009462, 2025). "Our data show that among all breast cancer subtypes, TNBC exhibits the highest levels of AXL expression and a strong association between AXL overexpression and the mesenchymal subtype of TNBC, which is known for its increased metastatic potential and resistance to chemotherapy." (PMID 41009462, 2025). "Here, we focused on the receptor tyrosine kinase AXL that has been identified as a mediator for tumor progression and therapy resistance in various cancer types, including squamous cell tumors, small cell lung cancer, and breast cancer." (PMID 38391974, 2024). "Immunostaining was performed to assess AXL expression in human breast cancer cell lines." (PMID 38132919, 2023). "LncRNA GSEC promotes breast cancer progression by sponging the miR-202-5p/AXL Axis." (PMID 37842058, 2023). "Subsequent investigations demonstrated that knockdown of ABL kinase resulted in decreased TAZ mRNA expression and reduced binding between TAZ and its downstream target AXL, a receptor tyrosine kinase that promotes breast cancer bone metastasis, and breast cancer bone metastasis was inhibited." (PMID 37256184, 2023). "Wang and collaborators demonstrated AXL’s involvement in breast cancer resistance to adriamycin." (PMID 37265798, 2023). "In addition, RTKs regulate E1A through NFI-C and NFI-X inhibition and AXL expression and thus sensitize breast cancer cells to EGFR–tyrosine kinase inhibitor chemotherapy." (PMID 37433225, 2023). "Indeed, AXL downregulation or inhibition in cancer cells reduces the secretion of angiogenic factors leading to suppression of the angiogenic capacity of breast cancer cells both in vitro and in vivo." (PMID 35158733, 2022). "It displays AXL-selective antitumor and antimetastatic activity in murine models of breast cancer." (PMID 35813203, 2022). "Collectively, targeting AXL is a potential strategy for breast cancer treatment." (PMID 35414783, 2022). "In this context, AXL deletion in a preclinical model of HER2+ breast cancer almost completely abrogated the metastatic dissemination by blocking intravasation, extravasation and growth at the metastatic site, supporting a role for AXL in TGF-β-induced cell invasion." (PMID 35158733, 2022). "Therefore, the most lethal form of breast cancer remains a clinical challenge, despite converging preclinical evidence demonstrating the efficacy of AXL/TAM inhibitors combined with PD-1 blockade in TNBC models." (PMID 35572601, 2022). "Importantly, AXL was recently shown to be required to generate the hypoxic response in HER2+ breast cancer by regulating HIF-1α expression." (PMID 35158733, 2022). "AXL‐CAR‐T cells have the potential to be a viable treatment method in AXL‐positive breast cancer." (PMID 35762299, 2022). "Previous study had shown that the AXL gene could be a downstream effector of the tumor cell Epithelial-to-mesenchymal transitions (EMTs) required by the metastasis of breast cancer." (PMID 34838035, 2021). "In breast cancer, AXL was identified as a component of the ΔNp63α-driven hybrid EMT program." (PMID 34638349, 2021). "Moreover, another patient (case 2) exhibited a rare missense alteration in the AXL extracellular domain (T343M) that has been described in breast cancer." (PMID 33570712, 2021).
breast carcinoma (continued). "Although AXL has been shown previously to relay secondary resistance to EGFR and HER targeted therapies in a subset of breast and lung cancers, a marked increase of AXL expression and stability in our small cohort of relapsed breast cancer tumors was unexpected." (PMID 33850249, 2021). "Overall, our study provides a detailed landscape of dynamic regulation of tyrosine phosphorylation driven by AXL activation, which demonstrates the complexity of AXL signaling and reveals the role of AXL in modulating signaling networks to promote breast cancer progression." (PMID 34439388, 2021). "Indeed, in breast cancer cell lines, AXL physically interacts and phosphorylates ELMO1/2 at two tyrosine residues, and this is required for GAS6-induced RAC1 activation and cell invasiveness." (PMID 34638349, 2021). "Given the role of AXL in altering the immune system in breast cancer, a similar mechanism could be occurring in mammary tumorigenesis as well." (PMID 32148495, 2020). "Additionally, others have shown that AXL expression correlates with the presence of the estrogen receptor in breast carcinomas, indicating that despite high-level expression of AXL in TNBC, AXL is not restricted to TNBC tumors." (PMID 32148495, 2020). "Here, we provide a novel function of AXL in VM formation in breast cancer cells." (PMID 33374832, 2020). "In addition, we also found a significant inverse correlation between the levels of miR-34a and those of AXL in seven breast cancer cell lines." (PMID 33374832, 2020). "Other transcription factors have been implicated in the expression of AXL in other cancer types, but these have not been directly studied in breast cancer." (PMID 32148495, 2020). "In mouse breast cancer cells sorted into two groups based on the level of AXL expression, it was observed that cells expressing high levels of AXL were more tumorigenic than their low AXL-expressing counterparts." (PMID 32148495, 2020). "Collectively, these results suggest that AXL regulates the expression of EMT markers in MCF-7 cells and may provide evidence of an association between VM formation and invasiveness of breast cancer cells." (PMID 33374832, 2020). "Here, we define the AXL-regulated phosphoproteome in breast cancer cells." (PMID 32681075, 2020). "AXL expression has been shown to correlate with that of the estrogen (ER) and progesterone (PR) receptors in breast cancer, indicating that estrogen and/or progesterone could regulate AXL expression." (PMID 32148495, 2020). "Furthermore, AXL stimulates the self-renewal of stem cells from breast cancer, chronic myelogenous leukaemia, and glioblastoma." (PMID 32051483, 2020). "Next, we determined whether the knockdown of AXL can affect the formation of VM in AXL high-expressing breast cancer cells." (PMID 33374832, 2020). "AXL inhibitors are beginning to show efficacy in the clinic, and a deeper understanding of AXL's role in breast cancer could lead to a better identification of subsets of patients with potential to benefit from AXL-targeted therapy." (PMID 32148495, 2020). "Considering the importance of CSCs in tumor progression 26 and the well-known involvement of AXL in the control of breast cancer 28 and cutaneous tumor 29 stemness, we evaluated the effects of axl-148b conjugate on a 3D model of breast cancer mammospheres 30-32." (PMID 32174798, 2020). "In addition, VM formation was suppressed by AXL inhibition in MDA-MB-231, BT-549, and HS578T breast cancer cells with the highest AXL expression." (PMID 33374832, 2020). "Hence, future work should aim to determine the subtypes of breast cancer that would be candidates to AXL or PEAK1 inhibition to limit metastasis." (PMID 32681075, 2020). "Several transcription factors have been found to directly regulate AXL expression in breast cancer." (PMID 32148495, 2020). "The role of AXL in metastasis of other subtypes of breast cancer is less clear." (PMID 32148495, 2020).
breast carcinoma (continued). "Many studies have reported a role for AXL in invasion in various cellular models, including breast cancer cells, but whether it occurs through controlling invadopodia formation remains to be investigated." (PMID 31963783, 2020). "In addition to regulation by transcription factors, several other players have been shown to affect AXL transcript levels in breast cancer cells." (PMID 32148495, 2020). "The role of AXL in breast cancer is highly context-dependent, and therefore, it is possible that different biomarkers may be necessary for different breast cancer subtypes." (PMID 32148495, 2020). "The anti-AXL monoclonal antibody 20G7-D9 has also been shown to be effective in management of TNBC breast cancer xenografts and patient-derived xenografts, where it blocks signaling, prevents EMT, reduces tumor growth, decreases migration and invasion, and also decreases metastasis formation." (PMID 32148495, 2020). "Indeed, blocking estrogen through either use of an estrogen antagonist or estrogen deprivation results in lower AXL mRNA levels in HER2+ ER+ breast cancer cells that have acquired resistance to lapatinib." (PMID 32148495, 2020). "Together, our findings support the hypothesis that miR-34a-mediated AXL targeting affects VM formation and aggressive tumor features, and provides a novel molecular mechanism for VM formation in breast cancer cells." (PMID 33374832, 2020). "Moreover, AXL overexpression in MCF-7 breast cancer cells with the lowest AXL expression promoted VM formation." (PMID 33374832, 2020). "The role of AXL in cancer with a focus on therapeutic implications for breast cancer is discussed." (PMID 32148495, 2020). "The role of AXL in chemoresistance further suggests that a treatment approach inhibiting AXL in combination with inhibitors of other molecular targets could be an effective therapeutic strategy for breast cancer treatment." (PMID 32148495, 2020). "A direct role for AXL in promoting breast cancer metastasis has also been observed." (PMID 32148495, 2020). "Increased AXL expression has been detected in a variety of solid tumors (e.g., prostate cancer, breast cancer, osteosarcoma, etc.)and hematological malignancies including chronic lymphocytic leukemia, chronic myeloid leukemia, acute myeloid leukemia, multiple myeloma and mantle cell lymphoma." (PMID 31694201, 2019). "The ligand for AXL; Gas6 also has a notable role in breast cancer progression." (PMID 31844158, 2019). "AXL expression is a strong negative prognostic factor for human breast cancer survival and its expression is associated with spread of metastatic breast cancer." (PMID 29719832, 2018). "AXL is overexpressed in various cancers, and its expression levels correlate with a low survival rate in such cancers as lung, pancreatic, and breast cancer (14, –16)." (PMID 28034848, 2017). "Notably, we also found that higher expression of AXL is correlated with poor overall survival, advanced tumor stage, and lymph node status of breast cancer patients." (PMID 27590506, 2016). "Taken together, these data suggest that therapeutic strategies targeting AXL in combination with systemic therapies could improve responses to anti-cancer therapies and reduce breast cancer recurrence and metastases." (PMID 27829217, 2016). "We showed that AXL was also expressed in basal-like breast cancer cells." (PMID 28721387, 2016). "To further explore whether AXL was involved in E1A-mediated EGFR-TKI sensitization of breast cancer cells, we examined the phosphorylation and expression of AXL in E1A-transfected breast cancer cells." (PMID 27590506, 2016). "Similarly, in breast cancer cells, AXL expression correlates with the stem cell markers Isl1, Cdc2a, and Bglap1." (PMID 27834845, 2016). "Moreover, data from a recent study demonstrated that AXL phosphorylates and interacts with Elmo in breast cancer cells, leading to induction of the RAC pathway and, consequently, the promotion of cell invasion." (PMID 27829217, 2016).
breast carcinoma (continued). "In addition, we found that Hs578T breast cancer cell line expressing AXL was more sensitive to the anti-proliferative effect of DN10764 than two other AXL-negative breast cancer cell lines such as SK-BR-3 and T47D." (PMID 27829217, 2016). "Nevertheless, we note that FRA1-promotion of cell migration likely involves other AP-1 target genes such as MMPs and adenosine receptor A2B (ADORA2B) as described in breast cancer, uPA in colon carcinoma, receptor tyrosine kinase AXL in bladder cancer, and CD44 and c-Met in mesothelioma." (PMID 27144339, 2016). "Thus, AXL has been proposed a very promising target for the development of anti-metastatic breast cancer therapy." (PMID 27829217, 2016). "In addition, AXL expression is required for invasiveness, growth, and metastasis in in vivo breast cancer models." (PMID 27829217, 2016). "Finally, we performed a survival analysis to examine if AXL gene expression correlates with clinical outcomes of breast cancer patients." (PMID 26356563, 2015). "Forced ectopic AXL expression induces the highly invasive characteristics seen in MCF7 breast cancer cells from initial weakly invasive phenotypes, whereas using shRNA treatment to induce AXL knockdown decreases the invasive and migratory capabilities of highly invasive cancer cells." (PMID 25780909, 2015). "In addition, AXL is needed for MDA-MB-231 breast cancer cells to metastasize to the lungs in orthotopic models." (PMID 25780909, 2015). "Also compared to a panel of 80 breast carcinoma (BC) samples stained in parallel, including triple-negative samples and selected positive BC tissue controls, considerably higher AXL expression was observed in ES samples." (PMID 25528764, 2014). "Furthermore, two studies show that AXL is activated in breast cancer stem cells (BCSC) and AXL expression induces EMT through direct regulation of the expression of E-cadherin, N-cadherin, Slug and Snail." (PMID 25337673, 2014). "Restores lapatinib sensitivity in lapatinib-resistant breast cancer cells with AXL over expression." (PMID 25337673, 2014). "c-Kit/AXL tyrosine kinase inhibitor investigated in stromal tumors and in breast cancer." (PMID 25337673, 2014). "In addition, the multikinase inhibitor GSK1363089 that also targets AXL can restore lapatinib sensitivity in HER2-positive breast cancer cells that overexpress AXL." (PMID 25337673, 2014). "VIM and SNAI2 were highly expressed together with AXL in breast cancer cell lines MDA_MB_231, HS578T, and BT_549, for example, and may confer mesenchymal-like character to these lines." (PMID 22570691, 2012). "A study conducted on human breast cancer found that when SNAI2 (SLUG) and SNAI1 (SNAIL) are transfected into MCF10A cells, human breast cancer epithelial cells lose their epithelial-type shape and acquire mesenchymal-related characteristics, and this was linked to AXL increase." (PMID 38391974, 2024). "Furthermore, re-expression of C-mannosylation-deficient AXL in human breast cancer MDA-MB-231 cells lacking AXL by the CRISPR/Cas9 system resulted in reduction of vasculogenic mimicry formation." (PMID 39660536, 2024). "Thus, CIN tolerance mediated by c-Jun/AXL signaling may be a defining feature of stemness, contributing to breast cancer progression." (PMID 37809421, 2023). "Indeed, AXL is overexpressed in 50%–75% of breast cancer samples." (PMID 38132919, 2023). "Finally, while AXL has been the main TAM family member that has been investigated in breast cancer, future work should also consider the role of other TAM family members, especially given the demonstrated cross-talk between these receptors and the recent finding that protein S can stimulate AXL." (PMID 32148495, 2020). "However, it remains to be investigated whether miR-34a-mediated regulatory mechanisms are involved in VM formation by targeting AXL in breast cancer cells." (PMID 33374832, 2020). "Indeed, a role for AXL in the progression of various breast cancer subtypes has been identified." (PMID 32148495, 2020).